FGF21 (fibroblast growth factor 21)
Diseases named in the same sentence as FGF21 in open-access papers (continued):
Sharing a sentence is not in itself a finding about the gene and the disease.
Hepatic steatosis (continued). "Furthermore, exercise downregulates miR-212, whose elevated expression promotes the suppression of fibroblast growth factor-21 (FGF-21) suppression and exacerbates hepatic steatosis." (PMID 40682843, 2025). "FGF21 level < 251 pg/mL was found to be a reliable threshold to rule out hepatic steatosis (sensitivity = 84%; negative likelihood ratio = 0.3)." (PMID 40563517, 2025). "The decrease of hepatic steatosis under the influence of FGF21 is less effective in female rodents, but it is not conditioned by ovarian hormone status." (PMID 39302236, 2024). "Liver tissue H&E staining also verified that OVX increased fat deposition in the liver and caused hepatic steatosis in female mice, while FGF21 LKO failed to reverse (p > 0.05) the OVX-induced liver weight gain and hepatic steatosis in OVX mice." (PMID 37834368, 2023). "In addition, FGF21 reduced the number of pro-fibrotic macrophages in the injured liver, potentially explaining why FGF21 counteracts all features of NASH, including hepatic steatosis, inflammation, and fibrogenesis." (PMID 36648330, 2023). "The PCB126 exposure induced various manifestations of hepatic steatosis, including liver volume and weight gain, increased vacuolization/lipid accumulation, hepatic TG, hepatic FFA and elevated plasma levels of native FGF21 in mice fed a SD or HFD." (PMID 36012166, 2022). "In a study using mice with constitutive expression of human AHR specifically in the liver, fibroblast growth factor 21 (FGF21) could be identified as a direct AHR target and a major mediator of both hepatic steatosis and systemic insulin hypersensitivity." (PMID 34075438, 2021). "These markers have been linked previously to FGF21 levels during hepatitis B infection in non-HIV settings, and hepatic steatosis in HIV settings." (PMID 34972147, 2021). "FGF-21 is known to increase metabolic flux and to reduce hepatic steatosis, but the mechanisms responsible for these effects are not fully discovered." (PMID 32069846, 2020). "The reduction in hepatic steatosis by FGF21 is independent of AMPK-dependent inhibition of acetyl CoA carboxylase (ACC)." (PMID 33381084, 2020). "In addition, irisin leads to fibroblast growth factor-21 (FGF-21) upregulation through the PPAR signaling pathway, especially PPAR-α, which can subsequently improve insulin sensitivity and hepatic steatosis." (PMID 28592311, 2017). "We attribute the difference in morbidity and mortality in mice lacking FGF21 between the two diets to the fact that ethanol and high fat diet have a synergistic negative effect on fatty liver disease, an interaction that has been demonstrated in humans." (PMID 29107287, 2017). "Wang further found that the injection of recombinant murine FGF21 reduces IL-6, TNF-α, and leptin mRNA levels in WAT of monosodium glutamate-induced obese rats, with the improvement of glucose tolerance, lipid metabolic spectrum, and hepatic steatosis." (PMID 27616737, 2016). "We also showed that in vitro FGF21 suppressed lipolysis in mouse adipose tissue explants freshly prepared from overnight fasted mice, suggesting that CREBH-induced FGF21 suppressed adipose tissue lipolysis to ameliorate hepatic steatosis." (PMID 27301791, 2016). "Notably, FGF21 has previously been shown to stimulate hepatic FAO and to prevent hepatic steatosis following ingestion of lipid-laden milk." (PMID 27367842, 2016). "Without PPARα, the expression levels of its target genes, including Fgf21, do not increase after birth, which promotes the build up of fats in liver cells, a condition known as liver steatosis." (PMID 27367842, 2016). "FGF-21 also decreases hepatic lipogenesis, upregulates enzymes for hepatic fatty acid oxidation, and has been shown to reverse hepatic steatosis in mice and non-human primates." (PMID 27182456, 2016).
Hepatic steatosis (continued). "Interestingly, overexpression of FGF21 ameliorated hepatic steatosis and NASH symptoms of KD-fed Creb3l3−/− mice, suggesting that FGF21 is one of the major CREBH targets that help alleviate steatosis and NASH." (PMID 27301791, 2016). "In a parallel study, we showed that lack of FGF21 exacerbated chronic alcohol exposure-induced fatty liver through SIRT-1-mediated fatty acid β-oxidation (unpublished observations)." (PMID 26092866, 2015). "The long-acting Fc-FGF21 fusion protein efruxifermin, along with the recombinant FGF21 analogs pegozafermin and pegbelfermin (BMS-986036), have demonstrated efficacy in improving metabolic parameters and reducing hepatic steatosis and inflammation levels in clinical trials." (PMID 40004572, 2025). "In addition, FGF21 levels were increased at 3, 5, and 10 days of HFD‐MetR, indicating a rapid hepatic response; FGF21 analogs are being considered as therapeutic treatments for fatty liver and metabolic disease." (PMID 40526038, 2025). "In clinical terms, higher FGF-21 levels were shown in patients with NAFLD than in individuals without NAFLD in most, but not all studies; similarly, data on circulating FGF-21 levels between patients with simple hepatic steatosis and steatohepatitis are inconclusive." (PMID 40465044, 2025). "Therefore, we conclude that nutritional intervention can be effective to reduce hepatic steatosis in female mice, yet FGF21 was not." (PMID 35998055, 2022). "In this study, the injection of HFD-induced obese mice with MS-275 prevented hepatic steatosis by reducing de novo lipogenesis and increasing lipolysis and mitochondrial oxidation, by increasing the expression of oxidation-related genes, such as PPARα, MCAD, CPT1b, and FGF21." (PMID 36077368, 2022). "Our results regarding the body weight and fatty liver score increases after doxepin treatment in obese mice are potentially attributable to the reduction in the serum levels of FGF-21, which attenuated protection against NAFLD (including nonalcoholic fatty liver and nonalcoholic steatohepatitis)." (PMID 33809508, 2021). "However, studies conducted in humans using FGF21 analogs have not shown a significant effect of these compounds on body weight or glycemic control, although a beneficial effect on hepatic steatosis has been observed." (PMID 33227979, 2020). "Moreover, QSPHK1 mice had alleviated hepatic triglyceride accumulation and had high-fat-diet-induced hepatic steatosis that occurred as a result of reduced lipogenesis and enhanced fatty acid oxidation, which were mediated by the AMPK/ACC axis and the FGF21/adiponectin axis." (PMID 33208918, 2020). "The observation that such changes in FGF21 levels do not occur in obese females, which instead exhibit features of unresolved ER (endoplasmic reticulum) stress, led us to suggest that the hepatic steatosis induced by the cafeteria diet in mice is directly related to ER stress." (PMID 31315289, 2019). "Lack of this adaptive ability in FGF21 KO mice further exacerbated alcohol-induced liver steatosis." (PMID 27498701, 2016). "Future investigations of how FGF21 alters fibrosis, protein translation, and cell proliferation in lipodystrophic and control livers could explain the observed decrease in liver size but not hepatic steatosis." (PMID 40663389, 2025). "FGF21 KO had no impact on body weight, glycaemic traits, or MASH histological endpoints, including hepatic steatosis, NAS score, lobular inflammation, ballooning degeneration, fibrosis stage, or the liver transcriptome." (PMID 40604130, 2025). "A long-acting FGF21 analogue, pegbelfermin, administered once a day at a dose of 10 or 20 mg for 16 weeks to overweight or obese humans with NASH reduced hepatic steatosis without changes in body weight or bone mineral density." (PMID 37249754, 2023).
Hepatic steatosis (continued). "An additional novel finding of this study was that changes in liver steatosis, as reflected by the surrogate marker HSI, were not correlated with FGF-21 changes, despite previous studies suggesting that FGF-21 reflects liver fat accumulation." (PMID 37999215, 2023). "Major biomarkers in our index are FGF21, FGF19 and A/L, which have not been used in previous biomarker panels for the prediction of fatty liver." (PMID 35663311, 2022). "The protection against diet-induced hepatic steatosis present in OPA1 BAT KO and OPA1/FGF21 BAT DKO mice was no longer observable in the absence of ATF4 induction in OPA1 BAT KO mice." (PMID 33944779, 2021). "First, the function and regulation of miRNA are complex, FGF21 may not be the only and the master target gene regulated by uric acid, further investigations are required to clarify the detailed downstream mechanisms of miR-149-5p on uric acid-induced hepatic steatosis." (PMID 32070295, 2020). "Subgroup analysis showed higher FGF-21 levels in patients with nonalcoholic steatohepatitis (NASH) compared to controls (SMD: 1.30; 95% CI: 0.35, 2.24; p = 0.007), but not between hepatic steatosis and controls, or hepatic steatosis and NASH." (PMID 40465044, 2025). "Similar to GDF15, FGF21 reduces the body weight through a non-adipose tissue effect; increases insulin sensitivity, adaptive thermogenesis, and uncoupling protein 1 (UCP1)-independent EE; and reverses hepatic steatosis." (PMID 33718833, 2021).
metabolic syndrome (245 papers, 2010 to 2026). A cluster of metabolic risk factors for CARDIOVASCULAR DISEASES and TYPE 2 DIABETES MELLITUS. "In a study including multi-ethnic populations (non-Hispanic white, African American, Hispanic American and Chinese American), baseline characteristics showed that elevated FGF21 level was associated with the prevalence of metabolic syndrome." (PMID 40356318, 2025). "This research identified FGF-21, Metrnl, nesfatin-1, and sortilin as potential biomarkers associated with the development of critical elements of metabolic syndrome." (PMID 40559404, 2025). "On the contrary, available data from clinical trials indicating beneficial effect of FGF21 analogues in managing weight loss, hyperinsulinemia and dyslipidemia are promising but of insufficient quality." (PMID 39302236, 2024). "In contrast, the expression of fibroblast growth factor 21 (FGF21), a molecule associated with metabolic syndrome and liver disease, was significantly reduced (37.9 ± 6.8 vs. 107.8 ± 10.1, p < 0.001)." (PMID 36140410, 2022). "Surprisingly, however, Zhang and colleagues found in 2008 that serum FGF21 was significantly increased in obese patients and associated with increased risk of the metabolic syndrome, suggesting FGF21 as potential biomarker for metabolic diseases." (PMID 36034414, 2022). "Elevated serum FGF21 levels are associated with metabolic syndrome, suggesting a state of FGF21 resistance." (PMID 36235821, 2022). "Based on strong preclinical evidence of the therapeutic effect of FGF21 in metabolic syndrome, clinical studies were conducted to evaluate the effect of FGF21 variants or analogs." (PMID 34513950, 2021). "On the other hand, there is evidence which suggests that cardiovascular disease is associated with increased levels of FGF21, therefore, the results found in this study showed a relationship between FGF21 and dyslipidemia in the HIV-positive population." (PMID 34019585, 2021). "Although an increased fibroblast growth factor 21 (FGF21) level was related to mild cognitive impairment (MCI) in metabolic syndrome patients, any association regarding FGF21 and MCI in thalassemia patients as well as mechanistic insight are questionable." (PMID 33850218, 2021). "F0AT1 (SLC6A19) inhibitor ameliorates the lipotoxicity and dyslipidemia to induce endogenous fibroblast growth factor 21 (FGF21) to treat fatty liver associated diseases." (PMID 34884968, 2021). "Considering the fact that metabolic syndrome is the key risk factor for endometrial cancer, the examination of serum levels of FGF21 and FGF23 in endometrial cancer patients appears warranted." (PMID 32570721, 2020). "The investigation of the exercise response in FGF21-deficient mice has shown that FGF21 action is necessary to achieve full metabolic benefits of exercise against the metabolic syndrome." (PMID 31546675, 2019). "Similar to our results, another study provided evidence that serum FGF21 levels mediate the association between metabolic syndrome and colorectal cancer risk." (PMID 31408968, 2019). "The beneficial effects of WPJ on these metabolic syndromes were associated with the improved FGF21 resistance and lipid metabolism." (PMID 26914024, 2016). "Pharmacological administration of FGF21 alleviates dyslipidemia and induces weight loss in obese animals." (PMID 26441837, 2015). "As shown in previous studies, serum FGF-21 levels are significantly higher in obese population with increased cardiovascular risk characterized by the evidence of metabolic syndrome in the obese subjects." (PMID 21206918, 2010). "Notably, subjects with FGF-21 levels equal to or exceeding 285.6 ng/mL exhibited an 11.4-fold increased risk of metabolic syndrome in comparison to those with lower levels." (PMID 40559404, 2025).
metabolic syndrome (continued). "Previous clinical research demonstrated that a high level of FGF21 was independently associated with cognitive impairment in patients with metabolic syndrome, however, exercise interventions could reduce FGF21 levels in obese women and elderly men." (PMID 40468210, 2025). "FGF21 is therefore viewed as a key integrator of a diverse range of physiological responses to states of energy restriction, many of which underlie desirable alterations in metabolism that confer resistance to clinical manifestations of metabolic syndrome." (PMID 40149686, 2025). "Understanding the effects of FGF19 and FGF21 on bone metabolism is important as FGF19 and FGF21 analogues may be used to treat disorders associated with the metabolic syndrome in future." (PMID 39341924, 2024). "In this study, we also incorporated plasma biomarkers traditionally used to study and diagnose metabolic and mitochondrial disorders, such as fibroblast growth factor 21 (FGF21), also linked to metabolic syndrome, and coenzyme Q10 (CoQ), both potential surrogates of MRC dysfunction." (PMID 39125986, 2024). "However, contrary to the observations in animal models, there are also studies that reported high circulating FGF21 levels in humans to be associated with metabolic syndrome and dyslipidemia." (PMID 37374349, 2023). "Besides, FGF21 is positively correlated with hypertension both in elderly outpatients and in youths at risk for metabolic syndrome." (PMID 37724523, 2023). "It is concluded that SSB intake may impact FGF21 concentrations and could contribute to the increased FGF21 concentrations observed in subjects suffering from metabolic syndrome that is possibly associated with decreased FGF21 responsiveness." (PMID 36235821, 2022). "FGF21 is also associated with poor metabolic health, with serum FGF21 levels being positively correlated with adiposity, fasting insulin and triglycerides, and increased risk of metabolic syndrome associated with high FGF21." (PMID 35017468, 2022). "Finally, we found that the plasma concentration of FGF21, a factor associated with metabolic syndrome (MetS) in humans, was elevated in the serum." (PMID 35505192, 2022). "And it is proposed that sweet-taste food may contribute to the increased FGF21 observed in subjects with metabolic syndrome that is possibly associated with decreased FGF21 response (FGF21 resistance)." (PMID 36618930, 2022). "As a result, FGF-21 may also serve as a biomarker indicating increased risk for the development of metabolic syndrome." (PMID 33924457, 2021). "We thus hypothesized that increased levels of FGF21 observed in patients with the metabolic syndrome are caused by an enhanced activity of inflammatory cytokines such as IL-1β." (PMID 33846498, 2021). "This study was designed to investigate whether serum FGF21 level was also associated with the metabolic syndrome-related cardiovascular disease, atherosclerosis, and its clinical features in a Chinese cohort." (PMID 23981342, 2013). "Indeed, KLBKO mice are totally refractory to FGF21-induced normalization of glucose homeostasis, attenuation of dyslipidemia, elevation of energy expenditure and weight loss." (PMID 23209629, 2012). "Further studies are warranted to determine whether elevated serum FGF-21 is causally related to dyslipidemia or is a compensatory response to CHD." (PMID 21206918, 2010). "Similarly, elevated concentrations in FGF21 are found in patients suffering from a lipodystrophy condition, which may be associated with the development of IR, metabolic syndrome and cardiovascular disease." (PMID 34019585, 2021). "FGF21 has received intense attention in the scientific literature in the context of metabolic syndrome due to the generally beneficial effects observed on systemic parameters such as glucose homeostasis, insulin sensitivity, and systemic inflammation." (PMID 40149686, 2025).